HMGB1 (high mobility group box 1)
Diseases named in the same sentence as HMGB1 in open-access papers (continued):
Sharing a sentence is not in itself a finding about the gene and the disease.
Granuloma (3 papers, 2011 to 2022). A compact, organized collection of mature mononuclear phagocytes, which may be but is not necessarily accompanied by accessory features such as necrosis. "Studies have shown that HMGB1 was predominantly localized in the cytoplasm of hepatocytes surrounding schistosome-induced granulomas in the livers of mice with acute schistosomiasis as well as the nuclei of hepatocytes during chronic infections." (PMID 35335612, 2022). "Based on immunohistochemistry, HMGB1 was predominantly localized in the cytoplasm of hepatocytes surrounding the schistosomotic granuloma in the livers of mice with acute schistosomiasis." (PMID 30258438, 2018). "In mice where the secretion of HMGB1 was inhibited, significantly more isolated granulomas were noted, and these granulomas were smaller." (PMID 30258438, 2018).
hearing loss (3 papers, 2021 to 2024). "In a murine model of noise-induced hearing loss, inhibition of HMGB1 expression in the cochlea attenuates oxidative stress and inflammation." (PMID 35573665, 2022). "FPS-ZM1 could resist the ototoxicity of cisplatin by suppressing the HMGB1/RAGE signal pathway, and it may be considered the new otoprotective potential strategy for hearing loss." (PMID 38169643, 2024).
Henoch-Schonlein purpura (3 papers, 2019 to 2020). "We also found that the serum HMGB1 level of 16 Henoch– Schonlein purpura patients was significantly lower after treatment with glycyrrhizin." (PMID 33133061, 2020). "In our previous study, we have found increased serum levels of HMGB1 in patients with Henoch– Schonlein purpura (HSP), allergic vasculitis (AV), and urticarial vasculitis (UV) and altered HMGB1 distribution in lesional skin in patients with HSP." (PMID 33133061, 2020). "Elevation of HMGB1 has also been detected in other vasculitic settings, such as IgA-vasculitis (formerly Henoch-Schonlein's purpura) and Kawasaki disease." (PMID 31695699, 2019). "In addition, HMGB1 overexpression (messenger RNA (mRNA) and protein levels) has been associated with an increase in the apoptosis of HUVEC co-cultured with peripheral blood mononuclear cell (PBMC) supernatant from patients with Henoch-Schonlein purpura." (PMID 30674349, 2019).
Hepatosplenomegaly (3 papers, 2014 to 2021). Simultaneous enlargement of the liver and spleen. "This is corroborated by the fact that although the CRP levels in systemic JIA patients presenting with hepatosplenomegaly or serositis were very high, HMGB1 was a more sensitive indicator (a diagnostic sensitivity for HMGB1 was 94% while for CRP was 64%)." (PMID 25516724, 2014). "There is a positive correlation between serum HMGB1 and ESR, CRP, and α2 globulin, and high levels of serum HMGB1 are also associated with hepatosplenomegaly or serositis in systemic onset type JIA." (PMID 33140586, 2021). "The CRP levels of systemic JIA patients presenting with hepatosplenomegaly or serositis were also significantly higher but HMGB1 was more sensitive than CRP in detecting hepatosplenomegaly or serositis in these patients, as shown by receiver operating characteristics (ROC) curve assessment." (PMID 25516724, 2014). "Additionally, high level of serum HMGB1 was related to hepatosplenomegaly or serositis in systemic onset JIA." (PMID 25516724, 2014). "Previous studies have demonstrated that HMGB1 levels were related to destructive JIA and more sensitive than CRP in detecting hepatosplenomegaly or serositis among patients with systemic JIA." (PMID 34247641, 2021). "Among the study participants with systemic onset JIA, levels of HMGB1 were significantly higher in patients with hepatosplenomegaly and serositis compared to those without these clinical characteristics (27695,03 and 12678,06 pg/ml; P < 0.001)." (PMID 25516724, 2014).
herpesvirus infection (3 papers, 2011 to 2024). "During herpesvirus infections, nuclear HMGB1 can bind to viral proteins, thereby facilitating herpesvirus replication." (PMID 39693295, 2024). "HMGB1 recently emerged as a key soluble factor in the pathogenesis of various infectious diseases, but nothing is known of its behaviour during herpesvirus infection." (PMID 21283827, 2011).
hip fracture (3 papers, 2020 to 2024). Traumatic or pathological injury to the hip in which the continuity of either the femoral head, femoral neck, intertrochanteric or subtrochanteric regions is broken. "Increased systemic HMGB1 levels following experimental hip fracture have been recently described, supporting this hypothesis." (PMID 36131923, 2022). "Based on these previous findings, we asked whether different anesthetic techniques would be able to lead to a difference in perioperative HMGB1 levels in elderly hip fracture patients undergoing surgical treatment." (PMID 32466360, 2020).
idiopathic inflammatory myopathies (3 papers, 2011 to 2023). "HMGB1 was observed extranuclearly in muscle biopsies from patients with idiopathic inflammatory myopathies, and exposure of the isolated skeletal muscle to HMGB1 caused an irreversible decrease in Ca2+ release from the sarcoplasmic reticulum." (PMID 21798087, 2011).
leiomyosarcoma (3 papers, 2024 to 2025). An uncommon, aggressive malignant smooth muscle neoplasm, usually occurring in post-menopausal women. "Bezu L, Kroemer G. High circulating HMGB1 indicates good prognosis in patients with advanced leiomyosarcoma under chemoimmunotherapy." (PMID 40526331, 2025). "In conclusion, despite encouraging trends, it would be premature to interpret increased HMGB1 as an unequivocal sign of good prognosis in patients with advanced leiomyosarcoma treated with doxorubicin, dacarbazine and nivolumab." (PMID 39572927, 2024). "Recent data, published in a Phase 1b trial, demonstrated that an ICD-associated surge in the plasma concentration of high-mobility group box 1 (HMGB1) indicates favorable prognosis in patients with advanced leiomyosarcomas treated with the combination of doxorubicin, dacarbazine and nivolumab." (PMID 39572927, 2024). "The combination leverages ICD induced by doxorubicin (HMGB1/ATP release) and synergizing with nivolumab’s PD-1 blockade to enhance T cell activation and overcome tumor immune evasion in advanced leiomyosarcoma, indicating that ICD–ICI synergy may enhance T cell activation and reduce immune escape." (PMID 40785846, 2025).
lymphedema (3 papers, 2017 to 2021). Excess fluid collection in tissues, causing swelling. "In support of this, we found that blockade of HMGB1 in the mouse tail lymphedema model inhibited inflammatory lymphangiogenesis." (PMID 30936872, 2019). "Two common DAMPs, high mobility group box 1 (HMGB1) and heat shock protein 70 (HSP-70), were found to be highly expressed in mouse tail-lymphedema tissues and 5-mm punch biopsies of human lymphedematous tissue compared to unaffected sites." (PMID 34733847, 2021).
macrophage activation syndrome (3 papers, 2019 to 2024). A complication of rheumatic disease that is caused by excessive activation and uncontrolled proliferation of T lymphocytes and well-differentiated macrophages. "The present report, where the incorrect data were removed, reaffirms the key information communicated at the time, and can be correctly cited as the first description of dynamically expressed systemic HMGB1 levels related to clinical courses during macrophage activation syndrome." (PMID 33975537, 2021).
malignant glioma (3 papers, 2014 to 2018). A grade III or grade IV glioma arising from the central nervous system. "A recent study indicated that necrotic cells can release HMGB1 into the extracellular environment, and necrosis is a characteristic feature of malignant gliomas." (PMID 25574225, 2015).
microcephaly (3 papers, 2020 to 2024). A congenital or acquired developmental disorder in which the circumference of the head is smaller than normal for the person's age and sex. "Within this minimal region, the pathogenic role of HMGB1 in the 13q12.3 microdeletion syndrome has been further implicated in a recent study reporting the association of heterozygous loss-of-function sequence variants in HMGB1 with developmental delay and microcephaly." (PMID 39635340, 2024). "Furthermore, a recent report has identified HMGB1 depletion as a candidate causing intellectual disability and microcephaly in human." (PMID 32708917, 2020). "The current findings that HMGB1 depletion causes a disrupted expression of several genes that are required for neurogenesis and neuronal migration support the finding that HMGB1 depletion during embryonic development causes microcephaly and intellectual disability." (PMID 32708917, 2020).
middle ear cholesteatoma (3 papers, 2015 to 2023). "This is the first study indicating the elevated levels of HMGB1 in sEVs derived from plasma of patients with middle ear cholesteatoma." (PMID 37998605, 2023). "In the microenvironment of middle ear cholesteatoma, RAGE/HMGB1 signaling might be, at least in part, responsible for molecular mechanisms that contribute to the development of the inflammatory disease." (PMID 25385222, 2015).
Miscarriage (3 papers, 2017 to 2023). A pregnancy that ends at a stage in which the fetus is incapable of surviving on its own, defined as the spontaneous loss of a fetus before the 22th week of pregnancy. "We thus hypothesise that the THBD-p.Trp153Gly mutation might perturb the interaction between THBD and HMGB1, thereby leading to local enhanced inflammation at the foetal-placental interface and contributing towards miscarriage aetiology." (PMID 29195508, 2017). "HMGB1 expression is significantly increased in villi and decidua in unexplained recurrent spontaneous abortion (URSA) group compared with those in the control group." (PMID 36761729, 2023). "This suggests that HMGB1 may also be involved in the development of miscarriage through the induction of autophagy." (PMID 37691930, 2023).
muscular dystrophies (3 papers, 2020 to 2024). "Disulfide HMGB1 was shown to be the prominent isoform across mouse models and patients of several muscular dystrophies suggesting HMGB1 is a target of ROS in these disease states." (PMID 39158383, 2024). "HMGB1 is a critical mediator of muscle regeneration and inflammation in multiple muscular dystrophies." (PMID 37856562, 2024). "TLR2/4 ligand HMGB1 is found in the cytoplasm of non-necrotic fibers from both humans and mice with muscular dystrophy, suggesting muscle cells actively secrete HMGB1." (PMID 32580419, 2020).
oesophageal adenocarcinoma (3 papers, 2020 to 2023). "Oesophageal adenocarcinoma expressed stronger cytoplasmic HMGB1 compared with normal epithelium (p = 0.002)." (PMID 31831860, 2020).
oral mucositis (3 papers, 2018 to 2023). Inflammation of the mucous membranes of any of the structures in the mouth. "HMGB1 as a known DAMP has been detected as a potential contributing factor in the pathogenesis of oral mucositis associated with the underlying oxidative stress and inflammation." (PMID 37511951, 2023). "HMGB1 has been suggested as an independent predictor of the severity of oral mucositis as well as a possible target for treatment." (PMID 37511951, 2023). "Additionally, HMGB1, as a potent innate immune mediator, has been shown to be involved in the onset of oral mucositis after chemotherapy and radiotherapy treatment." (PMID 37511951, 2023).
pancreatic adenocarcinoma (3 papers, 2020 to 2022). "Using the GSE15471 and TCGA-Pancreatic adenocarcinoma (PAAD) datasets, we analyzed the clinical importance of TOP2A-associated genes (HDAC1, HDAC2, HMGB1, HMGB2, NFYA, NFYB, NFYC, and SP1)." (PMID 32977589, 2020).
Pleural effusion (3 papers, 2013 to 2023). The presence of an excessive amount of fluid in the pleural cavity. "Soluble HMGB1 was comparable between pleural effusions (p = 0.872), with BPEs containing 53.07 ng/ml ± 11.21 and MPEs containing 48.89 ng/ml ± 12.13, respectively." (PMID 33013860, 2020). "Notably, levels of HMGB1 in pleural effusions were significantly higher than serum HMGB1 in both healthy and ccRCC cohorts (p = ≦0.0011), irrespective of effusion etiology." (PMID 33013860, 2020).
pleural plaques (3 papers, 2013 to 2019). "The ROC curves for serum HMGB1 levels showed that patients with MPM had an AUC of 0.674 relative to those with benign asbestos-related diseases (asbestosis or pleural plaques) and those who were healthy despite asbestos exposure (95% CI: 0.589-0.758)." (PMID 23617783, 2013).
polyarthritis (3 papers, 2015 to 2021). "HMGB1 is involved in the pathogenesis of this spontaneous polyarthritis and intervention with an HMGB1 antagonist can mediate beneficial effects." (PMID 33925132, 2021). "Indeed, monoclonal anti-HMGB1 antibodies have been shown to ameliorate polyarthritis and lupus-like disease in mouse models." (PMID 30619247, 2018). "Monoclonal HMGB1-targeting antibodies can ameliorate murine polyarthritis and lupus-like disease." (PMID 26596890, 2015).
Psoriasiform dermatitis (3 papers, 2017 to 2022). A skin abnormality characterized by redness and irritation, with thick, red skin that displays flaky, silver-white patches (scales). "HMGB1, and subsequently IL-18, determined the development of psoriasiform dermatitis in the imiquimod-treated mouse model." (PMID 35053208, 2021). "Therefore, the current study aimed to test the hypothesis that LXA4 and its analog can alleviate LPS-induced inflammation in NHEKs and IMQ-induced psoriasiform dermatitis by preventing the expression and translocation of HMGB1." (PMID 28769106, 2017). "Therefore, we investigated the effects of LXA4 and BML-111 on the HMGB1 signaling cascade and inflammation in lipopolysaccharide (LPS)-induced keratinocytes and imiquimod (IMQ)-induced psoriasiform dermatitis in mice." (PMID 28769106, 2017). "More importantly, we observed that BML-111 could diminish the expression and secretion of HMGB1 and protect against IMQ-induced psoriasiform dermatitis." (PMID 28769106, 2017).
psoriasis vulgaris (3 papers, 2022 to 2025). Plaque psoriasis is the most common presentation of psoriasis. "Compared with those in healthy donors, HMGB1 levels have been reported to be increased in the serum and skin lesions of patients with psoriasis vulgaris (PV), and while serum HMGB1 levels significantly increase with disease progression, they are downregulated after standard therapies are given." (PMID 40308590, 2025). "Serum levels of HMGB1, TLR4, IL‐23, and IL‐17A were quantified in 50 patients with moderate‐to‐severe plaque psoriasis and 30 healthy controls." (PMID 38414294, 2024). "Expression levels of serum HMGB1, TLR4, IL‐23, and IL‐17A in patients with psoriasis vulgaris and healthy control, which are denoted by (x ̄ ± s) or M (P25, P75)." (PMID 38414294, 2024).
pulmonary edema (3 papers, 2016 to 2023). Accumulation of fluid in the lung tissues causing disturbance of the gas exchange that may lead to respiratory failure. "Marked reductions in pulmonary edema further strengthened the lung protection capacity of the composition, possibly through a reduction in extracellular HMGB1 and hence improving the phagocytic activity of alveolar macrophages." (PMID 37764336, 2023).
retinal disease (3 papers, 2012 to 2022). "Identification of TLR modifiers or biomarkers (e.g., HMGB1 or DAMPs) in the vitreous and/or retinal tissue of patients with retinal disease will provide essential cues to develop selective or targeted inhibitors against them." (PMID 38983565, 2022). "The extracellular HMGB1 interacts with RAGE and TLR receptors in retinal diseases to actuate inflammatory pathways." (PMID 35269741, 2022). "Several endogenous TLR4 activators are upregulated during photoreceptor oxidative injury in vivo, such as HMGB1, suggesting that they may be a source of TLR4 activation during retinal disease." (PMID 22615780, 2012).
rheumatic diseases (3 papers, 2016 to 2023). "Only by breaking through these limitations and detecting the level of HMGB1 more sensitively can we ensure that targeting HMGB1 will bring more benefits to patients with rheumatic diseases." (PMID 35250993, 2022). "This review article summarizes the physiological function of HMGB1, the post-translational modification of HMGB1, its interaction with different receptors, and its recent advances in rheumatic diseases and strategies for targeted therapy." (PMID 35250993, 2022). "In rheumatic diseases, anti-HMGB1 mAb (m2G7) was a relatively well-studied antibody that played an anti-inflammatory role in collagen-induced arthritis." (PMID 35250993, 2022). "In the past 20 years, the role of HMGB1 in rheumatic diseases has been extensively studied." (PMID 35250993, 2022). "However, we should also recognize the complexity of the role of HMGB1 in rheumatic diseases and the difficulty of extracellular HMGB1 detection." (PMID 35250993, 2022). "Here we summarize the characteristics and new insights of HMGB1 in rheumatic diseases." (PMID 35250993, 2022). "This review mainly describes the new advances of HMGB1 in rheumatic diseases." (PMID 35250993, 2022). "HMGB1 could represent a player in the pathogenesis of rheumatic diseases and an attractive target for molecular interventions." (PMID 27242789, 2016). "Thus, targeting HMGB1 is a promising therapeutic strategy for treating rheumatic diseases." (PMID 35250993, 2022).
RSV bronchiolitis (3 papers, 2021 to 2023). "As the inhibition of MLKL or targeting of HMGB1/RAGE pathway attenuates the release of pro-inflammatory HMGB1 and decreases viral load, this suggests that the pharmacological targeting of these pathways may be of benefit for the treatment of severe RSV bronchiolitis." (PMID 35712662, 2022). "Increased levels of HMGB1 have also been observed in the lungs of RSV-infected rat pups, peripheral blood, and nasopharyngeal aspirates in infants with RSV bronchiolitis." (PMID 37798799, 2023). "RSV infection fails to induce apoptosis, but necroptosis, leading to HMGB1 release and neutrophilic inflammation that both contribute to RSV bronchiolitis pathogenesis in RSV-infected hAECs and murine pneumovirus infected mice." (PMID 34594225, 2021).
Salmonella Infections (3 papers, 2016 to 2023). Infections with bacteria of the genus SALMONELLA. "HMGB1 release was significantly induced in the jejunum with Salmonella infection compared to the GF group." (PMID 36768650, 2023). "We observed that Salmonella counts, phagocytic cell (MDMI and MDMII) counts, and pro- and anti-inflammatory cytokine (TNF-α, HMGB-1 and IL-10) counts increased as Salmonella infection (load) increased." (PMID 27556404, 2016). "In the case of Salmonella infection, our results demonstrate that RAGE activation is engaged by the binding of the protein HMGB1." (PMID 34099666, 2021).